SLC27A2 (solute carrier family 27 member 2)
Diseases named in the same sentence as SLC27A2 in open-access papers (continued):
Sharing a sentence is not in itself a finding about the gene and the disease.
tumor (continued). "In line with our results, recent studies have shown that SLC27A2-specific inhibitor could substantially delay tumor growth and increase responses to immune checkpoint inhibitors in tumor model mice." (PMID 36869083, 2023). "Targeting SLC27A2/FATP2 or PPARs may identify new anti-tumor strategies, especially in metabolic therapy, immunotherapy, targeted therapy, immunometabolism or combinations." (PMID 37041476, 2023). "Similarly, SLC27A2 is the most upregulated gene comparing TCGA tumor types to pooled GTEx control group, especially in KIRC, COAD, KIRP, and LIHC." (PMID 37397501, 2023). "Therefore, the up-regulated key TME-related genes SLC27A2, KLRB1, IGKV1OR2-108 and IGHV1-12 in the low-risk score group inhibit tumor progression by affecting the secretion of neutrophils, NK cells and immunoglobulin." (PMID 36869083, 2023). "The preliminary results indicated that knockdown of SLC27A2 may reduce tumor burden in preclinical animal model." (PMID 37041476, 2023). "Therefore, up-regulated SLC27A2, KLRB1, IGKV1OR2-108 and IGHV1-12 in the low-risk score group synergistically inhibit tumor progression and activating immune response by regulating CD8+ T cells, NK cells and immunoglobulin." (PMID 36869083, 2023). "Furthermore, depletion of SLC27A2 reduced tumor proliferation (Ki67 staining, p = 0.004) and increased tumor apoptosis (cleaved Caspase-3 staining, p < 0.0001) without altering MYCN expression (p = 0.4)." (PMID 35764645, 2022). "Future studies remain necessary to determine whether SLC27A2 inhibition also interferes with immune cell functions and their metabolic dependencies to prohibit tumor growth." (PMID 35764645, 2022). "The results showed that overexpression of SLC27A2 reduced tumor weights and volumes in vivo." (PMID 35927229, 2022). "Genetic and pharmacological interference (via CB5) of SLC27A2 blocks NB tumor growth." (PMID 35764645, 2022). "In summary, SLC27A2 expression is diminished in ccRCC, and this lower SLC27A2 expression may accelerate tumor progression through CDK3-mediated EMT." (PMID 35927229, 2022). "Collectively, these data indicate that SLC27A2 is required for NB cell survival and tumor growth." (PMID 35764645, 2022). "Different tumor microenvironments and genetic backgrounds may influence SLC27A2’s physiological roles in different cancers." (PMID 35927229, 2022). "To further examine whether SLC27A2 is required for in vivo tumor growth, we orthotopically implanted MNA LAN5 shCTRL and shSLC27A2 cells into NCr nude mice." (PMID 35764645, 2022). "SLC27A2 is also expressed in immune cells, such as oncogenic polymorphonuclear myeloid-derived suppressor cells, and SLC27A2 inhibition blocks immune-suppressive activity in these cells, delaying tumor progression." (PMID 35764645, 2022). "SLC27A2 may promote tumor proliferation and migration through the change of C‐FOS expression, and our study provides a potential prognostic indicator and a treatment method for patients with DTC." (PMID 34854499, 2022). "Our study highlights the role of SLC27A2 in promoting tumor proliferation and invasion." (PMID 34854499, 2022). "Interestingly, nuclear staining of SLC27A2 was observed in a subset of tumor samples." (PMID 40647532, 2025). "This suggests that SLC27A2 may have tumor-promoting properties." (PMID 38753091, 2024). "In vivo, overexpreesion of SLC27A2 could inhibit tumor growth." (PMID 35927229, 2022). "Finally, through in vitro and in vivo experiments, we found that SLC27A2 could influence various biological functions of BC cells, including tumor nucleotide metabolism, lipid metabolism, and cell proliferation, establishing it as a valuable independent target for BC with significant research value." (PMID 38753091, 2024). "The protein levels of HPA demonstrated that MAP7 and SLC27A2 levels were lower, and SLC3A1 levels were higher, in tumor tissues than in normal samples, in accordance with the results of the TCGA-KIRC and RT-PCR." (PMID 36620592, 2022).
tumor (continued). "The expression of SLC27A2, SFRP2, KRT17 were up-regulated in tumor tissues (p<0.05), the expression of TAGLN was down-regulated (p<0.05), while those of NAT2 remained unchanged (p>0.05), compared with the levels in the corresponding normal tissues." (PMID 36479114, 2022). "SLC27A2 is necessary for NB survival, as both genetic interference and pharmacological inhibition via the small-molecule inhibitor CB5 impaired MYCN-induced tumor growth." (PMID 35764645, 2022). "The abnormal expression of SLC27A2 in DTC and its role in tumor progression encouraged us to study it further." (PMID 34854499, 2022). "Mechanistic and functional studies revealed that SLC27A2 orchestrates EMT through CDK3, partially reversing this process and inhibiting tumor progression." (PMID 35927229, 2022). "The analysis showed that HEATR1 was significantly increased, while SLC27A2 was significantly decreased in tumor samples compared to normal tissue." (PMID 40647532, 2025). "When A-172 cells with or without ectopic SLC27A2 expression were administered intracranially, the number of viable tumor cells (human Ki-67 positive cells) was significantly reduced in mice with SLC27A2-A-172 cells compared to that in control cells." (PMID 38719806, 2024). "We found that SLC27A2 was not related to sex or age (p > 0.05) but was significantly correlated with tumor size (p = 0.014), TNM stages (p = 0.005), LNM (p < 0.001), and extrathyroidal extension (p = 0.025)." (PMID 34854499, 2022). "Moreover, qRT-PCR verified seven apoptosis-related genes (APP, DOCK8, IFI44, MDK, SLC27A2, TNFAIP2, WNT5A) with at least 2 fold changes by means of 2−ΔΔCt method, finding that APP, SLC27A2 and WNT5A had a low expression, while DOCK8, IFI44, MDK, TNFAIP2 had a high expression in ccRCC tumor tissues." (PMID 33748185, 2021).
cancer (42 papers, 2009 to 2025). A tumor composed of atypical neoplastic, often pleomorphic cells that invade other tissues. "Disruptions in their function, potentially caused by SLC27A2 dysregulation, can significantly impact cancer cell behavior." (PMID 40647532, 2025). "Inhibitors like Lipofermata, which target FATP2 (the protein encoded by SLC27A2), have demonstrated efficacy in other cancers by disrupting fatty acid uptake and inducing apoptosis, illustrating a principle of targeting the protein’s activity regardless of its expression level." (PMID 40647532, 2025). "SLC27A2′s influence extends beyond normal metabolic function; its connection to lipid metabolism is particularly relevant in the context of cancer." (PMID 40647532, 2025). "While this finding raises the possibility of a previously unrecognized nuclear role for SLC27A2 in cancer cells, it should be interpreted with caution." (PMID 40647532, 2025). "This is supported by findings in other cancers, where SLC27A2 influences processes like fatty acid oxidation (FAO) and interacts with key regulators of lipid metabolism." (PMID 40647532, 2025). "In this cancer, SLC27A2 influences EMT transition by negatively regulating CDK3, whose low expression is associated with a poor prognosis." (PMID 41373732, 2025). "High HEATR1 and low SLC27A2 expression correlated with cancer progression, relapse, and overall survival in patients with high-grade ccRCC." (PMID 40647532, 2025). "While generally considered a tumor suppressor gene in different cancers, SLC27A2′s role in ccRCC is less clear." (PMID 40647532, 2025). "Solute carrier family 27 member 2 (SLC27A2) is important for FA transportation and metabolism and is related to cancer progression." (PMID 37041476, 2023). "In previous studies, solute carrier family 27 member 2 (SLC27A2) was reported to regulate cancer proliferation, metastasis, inflammation and immunosuppression." (PMID 37041476, 2023). "The ability of SLC27A2 overexpressing cells to invade was dramatically diminished while the ability of cancer cells with SLC27A2 koncked down to invade was dramatically rised." (PMID 35927229, 2022). "We further analyzed GSE129562 and GSE33630 datasets and observed that SLC27A2 expression was elevated in DTC tissues compared with that in the matched non‐cancer tissues." (PMID 34854499, 2022). "The results showed that SLC27A2 was notably downregulated in Gumz, Jones, Lenberg, and The Cancer Genome Atlas Kidney Renal Clear Cell Carcinoma (TCGA-KIRC) data." (PMID 35927229, 2022). "This suggests that strategies to modulate SLC27A2 activity could hold promise for treating various cancers." (PMID 40647532, 2025). "Studies have shown that SLC27A2 is elevated in cancers and promotes cancer progression." (PMID 37041476, 2023). "Therefore, further investigations are mandatory to better clarify the heterogeneous findings on SLC27A2 as an emerging potential cancer biomarker." (PMID 37397501, 2023). "In addition, it has been found that SLC27A2 is widely involved in the development of cancer." (PMID 38664735, 2024). "Targeting SLC27A2/FATP2 or PPARs might be a new strategy for cancer treatment." (PMID 37041476, 2023). "In TCGA-BRCA database, DCTPP1, SLC27A2, and IFNG were highly expressed in cancer tissues, while MYH3 was expressed at a low level in cancer tissues." (PMID 38753091, 2024). "The authors confirmed the downregulation of several genes in at least 7 cancer types, including ACOX3, PKC2, SLC27A4, and SLC27A2." (PMID 33562532, 2021). "Finally, RT-PCR showed that MAP7, SLC16A12, and SLC27A2 decreased, while SLC3A1 increased, in cancer cells." (PMID 36620592, 2022). "Additionally, we examined SLC27A2 expression in DTC and para‐carcinoma samples via the Immunohistochemistry (IHC) assay." (PMID 34854499, 2022).
infection (2 papers, 2017 to 2023). The state of being infected such as from the introduction of a foreign agent such as serum, vaccine, antigenic substance or organism. "ACSL5 has a preference for C16 to C20 substrates, whereas other acyl-CoA synthetases induced by infection (SLC27A2 and ACSBG2) are more active for VLCFA (C20 to C24)." (PMID 37862421, 2023).
SLC27A2 also shares sentences with these, for which no sentence is quoted: Hyperinsulinemia (4 papers); hepatoma (3); Hyperglycemia (3); kidney disease (3); type 2 diabetes (3); colon carcinoma (2); liver disease (2); metabolic disease (2); renal fibrosis (2); acute kidney injury (1); acute lymphoblastic leukemia (1); atherosclerosis (1); B-cell lymphoma (1); bladder tumor (1); chronic rhinosinusitis (1); colitis (1); cutaneous melanoma (1); cyst (1); cystinuria (1); diffuse large B-cell lymphoma (1); gallstones (1); glioma (1); Hypoinsulinemia (1); Impaired glucose tolerance (1); intrahepatic cholestasis (1); kidney (1); Lewis lung carcinoma (1); metastatic tumors (1); overnutrition (1); sarcoma (1).
A further 6 diseases each share a sentence with SLC27A2 in 1 paper.